LRRC47 (leucine rich repeat containing 47)
Synonyms: KIAA1185; RP1-286D6.3
Tractability: Small molecule: a structure with a bound ligand is known. PROTAC: ubiquitination databases record sites on it; its protein half-life has been measured.
Gene: Protein-coding gene on chromosome 1 (3,778,559 to 3,796,511, reverse strand). Ensembl gene ENSG00000130764.
Subcellular location (Human Protein Atlas): Nucleoli fibrillar center
Gene Ontology:
Molecular function: protein binding; RNA binding; phenylalanine-tRNA ligase activity
Biological process: phenylalanyl-tRNA aminoacylation
Genetic constraint (gnomAD): Loss-of-function variants: 28 observed, 30.2 expected, observed/expected ratio (o/e) 0.93, 90% interval 0.69 to 1.27. The synonymous counts are far from expectation, so gnomAD's model fits this gene poorly and the ratio says little. Missense variants: 689 observed, 641.92 expected, observed/expected ratio (o/e) 1.07, 90% interval 1.01 to 1.14. Synonymous variants: 413 observed, 299.52 expected, observed/expected ratio (o/e) 1.38, 90% interval 1.27 to 1.5.
Homologues: Orthologues: chimpanzee LRRC47 (99% identical), macaque LRRC47 (98% identical), guinea pig LRRC47 (88% identical), rat Lrrc47 (88% identical), mouse Lrrc47 (87% identical), dog LRRC47 (85% identical), pig LRRC47 (85% identical), tropical clawed frog lrrc47 (59% identical), zebrafish lrrc47 (53% identical), Caenorhabditis elegans Y54E10A.6 (30% identical). Paralogues in human: FARSB (16% identical).
Diseases named in the same sentence as LRRC47 in open-access papers:
LRRC47 is named in the same sentence as 5 diseases in open-access papers, as found by Europe PMC text mining. Sharing a sentence is not in itself a finding about the gene and the disease. The quoted sentences say what the papers report.
glioblastoma (1 paper, 2023). The most malignant astrocytic tumor (WHO grade IV). "Interestingly, in a particular subgroup of glioblastomas associated with a more favorable prognosis, the lnc-LRRC47-78 promoter is hypermethylated, resulting in its downregulation." (PMID 37835380, 2023).
prostate carcinoma (1 paper, 2023). A carcinoma that arises from epithelial cells of the prostate gland. "With siRNA screens, several of these were indicated in survival (DDX6, EIF4A3, PABPN1), growth (e.g., EIF5A, HNRNPH2, LRRC47, and NVL), and migration (e.g., NOL3 and SLTM) of prostate cancer cells." (PMID 37591798, 2023).
cancer (1 paper, 2023). A tumor composed of atypical neoplastic, often pleomorphic cells that invade other tissues. "Similarly, some progressors (CHMP4B, CSTF1, and LSM14B) and suppressors RBPs (ATP5F1A, GTF2E2, RTF1, ELAC2, LRRC47, and MRM3) have never been associated with COAD or READ, but present oncogenic properties in other cancer types." (PMID 37384253, 2023).
LRRC47 also shares sentences with these, for which no sentence is quoted: infection (1 paper); respiratory failure (1).